CXCL8 (C-X-C motif chemokine ligand 8)
Diseases named in the same sentence as CXCL8 in open-access papers (continued):
Sharing a sentence is not in itself a finding about the gene and the disease.
Obesity (continued). "Additionally, During the development of obesity-related diseases, chemokines such as CXCL5 and CXCL8, secreted by white adipose tissue, are highly expressed in the adipose tissue of obese subjects." (PMID 39334887, 2024). "Moreover, the lncRNA MIR3142HG, recently described as important mediator of the inflammatory response in Idiopathic Pulmonary Lung Fibroblasts positively regulating CXCL8 and CCL2 release, is specifically up-modulated in obesity." (PMID 32714872, 2020). "To assess whether ASCs could be recruited in response to CXCL1 secreted by tumours in obesity, we performed immunofluorescence analysis of CXCR1 and CXCR2, the receptors of CXCL1 and CXCL8." (PMID 27241286, 2016). "However, to our knowledge, the roles of CXCL8 within NK cells, monocytes, and eosinophils in the progression of obesity have not yet been identified." (PMID 35894174, 2022). "Obesity-induced increased levels of glucose and FFAs create stress in pancreatic islets, adipose tissue, liver, and muscle, resulting in increased local production and release of cytokines and chemokines such as IL-1β, TNFα, CCL2, CCL3, and CXC-chemokine ligand 8 (CXCL8, also known as IL-8)." (PMID 28018292, 2016).
ovarian carcinoma (295 papers, 2002 to 2026). A malignant neoplasm originating from the surface ovarian epithelium. "The chemokine IL-8 (CXCL8) has also been associated with poor prognosis and reduced survival in advanced epithelial ovarian cancer patients." (PMID 41149076, 2025). "Another study found that the chemokine CXCL8, also known as interleukin-8 (IL-8), is overexpressed in ovarian cancer and is associated with poor prognosis and resistance to chemotherapy." (PMID 37762405, 2023). "Levels of CXCL8 are elevated in the serum of ovarian cancer patients and are associated with poor prognosis and survival." (PMID 37762405, 2023). "Previous literature has implicated CXCL8 in promoting metastasis in pancreatic cancer, ovarian cancer, and CRC." (PMID 35879507, 2022). "Experimental evidence suggests that a higher expression of CXCL8 in ovarian cancer cells is associated with metastasis and angiogenesis." (PMID 35406529, 2022). "Ovarian cancer is associated with increased expression of the pro-angiogenic chemokine interleukin-8 (IL-8, CXCL8), which induces tumor cell proliferation, angiogenesis, and metastasis." (PMID 26267322, 2015). "CXCL8 signaling has also been associated with an increased resistance to cisplatin and paclitaxel in ovarian cancer." (PMID 24276377, 2013). "It is known that different cell types in the ovarian cancer tumor microenvironment might secrete CXCL8, including tumor-associated macrophages, neutrophils, and endothelial cells." (PMID 37765018, 2023). "In addition to CXCL12 and CXCL8, other chemokines have been implicated in ovarian cancer progression." (PMID 37762405, 2023). "We measured ROS and CXCL8 levels in serum and tissue samples from ovarian cancer patients, benign tumors, and healthy subjects." (PMID 39660100, 2025). "ROS and CXCL8 are potential new therapeutic target(s) and biomarker(s) for ovarian cancer development in the future." (PMID 39660100, 2025). "HDAC inhibition in ovarian cancer cells activates a signaling pathway that increases IL-8/CXCL8 expression through an IKK-dependent mechanism." (PMID 39949780, 2025). "In conclusion, our results demonstrate that high levels of ROS in ovarian cancer tissues lead to CXCL8 induction via activation of p70S6K1 and inhibition of GSK-3β." (PMID 39660100, 2025). "CXCL8, which is highly expressed in TAMs compared to resident peritoneal macrophages, has been shown to enhance ovarian cancer metastasis through EMT and Wnt/β-catenin signaling." (PMID 39937005, 2025). "CXCL8 has also been shown to promote cancer progression through autocrine signaling, reinforcing its importance in ovarian cancer TME." (PMID 39937005, 2025). "Our study found much higher levels of ROS and C-X-C motif chemokine ligand 8 (CXCL8) in ovarian cancer cells and tumor tissues." (PMID 39660100, 2025). "In this review, we summarize the recent findings on how IFNγ affects the tumor microenvironment and promotes tumor progression, with a special focus on ovarian cancer and on Bcl3, PD-L1 and IL-8/CXCL8 signaling." (PMID 39123403, 2024). "For instance, CXCL1 and CXCL8 have been found to stimulate ovarian cancer cell growth via activation of the p38 and Wnt/β-catenin pathway." (PMID 36969851, 2023). "Ovarian cancer cells also cause an increase in CXCL1 and CXCL8/IL-8 expression in omental human peritoneal mesothelial cells." (PMID 37108425, 2023). "The results showed that the levels of CXCL1 and CXCL8 in the plasma of ovarian cancer patients were significantly increased compared to healthy subjects." (PMID 37762405, 2023). "We identified CXCL1 and CXCL8 as chemokines induced by epinephrine and confirmed that their secretion in ovarian cancer cells increased in a dose-dependent manner following treatment with epinephrine, norepinephrine, and isoproterenol." (PMID 37762405, 2023). "CXCL1 and CXCL8 chemokines secreted by ovarian cancer cells bind to CXCR1 and CXCR2 receptors and promote cell proliferation, migration, and angiogenesis." (PMID 37762405, 2023).
ovarian carcinoma (continued). "To characterize the expression profile of CXCL8 in the ovarian cancer tumor microenvironment, we checked immunohistochemistry (IHC) staining in the human protein atlas (HPA)." (PMID 37765018, 2023). "We also found that catecholamines induce the secretion of CXCL1 and CXCL8 and increase ovarian cancer cell invasion by interacting with their corresponding receptors, which can be disrupted by specific inhibitors." (PMID 37762405, 2023). "CXCL8 can enhance the anti-anoikis function by activating the PI3K-Akt signaling pathway in ovarian cancer." (PMID 37377954, 2023). "In ovarian cancer, CXCL8 can recruit TANs in TME and induce the expression of Jagged2 (JAG2) in TANs which subsequently inhibit the activity of CD8(+) T cells." (PMID 35372515, 2022). "CXCL8 contributes to the recruitment of tumor-associated neutrophils that suppress CD8+ T-cell activity, partly depending upon Notch signaling in ovarian cancer." (PMID 35011369, 2021). "cDNA microarray data conducted by our group revealed overexpression of CXCL2 and CXCL8 in ovarian cancer (OC) microenvironment." (PMID 34038868, 2021). "The ovarian cancer cell stemness was promoted by the CXCL8 secreted from CAFs through the Notch3 signaling pathway." (PMID 35011369, 2021). "A further study demonstrated that genistein can suppress M2 polarization of macrophages and stemness of ovarian cancer through CXCL8/STAT3 signaling." (PMID 35011369, 2021). "One of the reasons for failure in advanced ovarian cancer is the escape from antiangiogenic therapy, and both CXCL8 and Bv8 synthesis by TANs has been suggested to be one of the participants." (PMID 30680411, 2019). "Ovarian cancer cells provoke recruitment of TANs to the tumor microenvironment by secreting large amounts of CXCL8 (IL-8), which can bind to both CXCR1 and CXCR2." (PMID 30680411, 2019). "In ovarian cancer, CXCL8 expression induction increases cell viability and proliferation and reduces apoptosis." (PMID 31756998, 2019). "One such chemokine is CXCL8 which is a known angiogenic factor and has also been shown to exert a mitogenic effect in cancers such as colon cancer, prostate and ovarian cancer." (PMID 30086759, 2018). "Elevated production of the cytokines CXCL8 and CXCL1 have been implicated in autocrine-based drug resistance in various tumor cell lines and in poor clinical outcome in ovarian cancer patients." (PMID 28915246, 2017). "Previous studies suggest that IKKβ regulates the expression of CXCL1, CXCL2 and CXCL8 in ovarian cancer cells." (PMID 26657155, 2016). "Our previous study demonstrated that proinflammatory chemokines such as CCL20, CXCL1-3 and CXCL8 are elicited in ovarian cancer cells via NF-κB- and EGFR-activated signaling pathways." (PMID 27723802, 2016). "Our previous studies demonstrated that TNF activated the nuclear factor-κB (NF-κB) signaling to induce proinflammatory chemokines such as CCL20, CXCL1-3 and CXCL8 in ovarian cancer cells." (PMID 27723802, 2016). "The underlying mechanisms likely involve the NFκB-regulated chemokine expression, since several studies have demonstrated that the expression of CCL2, CXCL1, CXCL2, and IL-8/CXCL8 is mediated by NFκB in ovarian cancer cells." (PMID 25790431, 2015). "When human ovarian carcinoma cell lines were implanted into the peritoneum of immunocompromised mice the expression of CXCL8 was directly correlated with neovascularization and inversely correlated with survival." (PMID 24971349, 2014). "CXCL-8 has been determined to play a significant role in mediating human ovarian carcinoma-derived angiogenesis and tumorigenesis." (PMID 24971349, 2014). "Despite either no or little activation of NF-κB, EGF is likely to broadly induce CCL20, CXCL1-3 and CXCL8 through Akt/Erk activation in ovarian cancer cells." (PMID 23800251, 2013). "CXCL8 has also been shown to be higher in ascites isolated from ovarian cancer patients than in ascites of women with benign tumors." (PMID 23800251, 2013).
ovarian carcinoma (continued). "In our previous study, inflammatory agents including bacterial endotoxin lipopolysaccharide (LPS) and proinflammatory cytokines interleukin-1 (IL-1) and TNF, induced CXCL1-3 and CXCL8 in ovarian cancer cells by involving NF-κB signaling." (PMID 23800251, 2013). "The fact that an EGF-induced increase in CXCL1 and CXCL8 was decreased by MAPK inhibitors in ovarian cancer cells indicates involvement of Akt or Erk signaling." (PMID 23800251, 2013). "Another study revealed that CXCL8 is inducible in cancer cells, and that it is highly produced and processed as N-terminally truncated form in the ascites of ovarian cancer patients." (PMID 24213462, 2012). "Advanced (less differentiated) ovarian cancer also overexpress CXCL8 in cyst fluids and tumor cells." (PMID 23300534, 2012). "This scenario has been predicted from an experimental model of ovarian cancer in which elevated intra-tumoural CXCL8 expression correlated with an increased infiltration of neutrophils and macrophages and a decreased tumourigenicity." (PMID 21285972, 2011). "Such an activity was reported for CXCL8 that acts as an autocrine growth factor for human ovarian cancer Hey-A8 cell line." (PMID 20049170, 2010). "Most chemokines sustain cancer cell proliferation and survival acting as autocrine factors, as reported for CXCL8 in Hey-A8 human ovarian cancer cells line blocked by specific neutralizing antibodies." (PMID 20049170, 2010). "The TNF-related apoptosis-inducing ligand (TRAIL) can trigger apoptosis in many malignant cells, but CXCL8 has been shown to block TRAIL-induced cell death by converting a TRAIL-sensitive ovarian cancer cell line (OVCAR3) into a TRAIL-resistant one." (PMID 16824216, 2006). "CXCL1 and CXCL8 were identified as being distinctive ovarian cancer markers." (PMID 40507922, 2025). "To evaluate whether CXCL8-mediated ovarian cancer cell invasion involves TRIM46 upregulation, we pre-treated ovarian cancer cells with reparixin, a CXCR1/2 inhibitor." (PMID 39937005, 2025). "In ovarian cancer, therapeutic strategies that inhibit CXCL8 or its receptors could reduce TAM-mediated cancer progression and metastasis." (PMID 39937005, 2025). "Among these, C-X-C motif chemokine ligand 8 (CXCL8) showed significantly elevated expression in peritoneal MQs (pMQs) from the ascites of ovarian cancer patients and macrophages stimulated by ovarian cancer cells." (PMID 39937005, 2025). "These pathways could represent central nodes that reconcile the seemingly discordant regulation of FN-1 and CXCL8 between different ovarian cancer cell lines." (PMID 41382114, 2025). "CXCL8 has been reported to drive EMT via the Wnt/β-catenin pathway in ovarian cancer cells." (PMID 39937005, 2025). "Additionally, C-X-C motif chemokine ligand 8 (CXCL8) was identified as being highly expressed in peritoneal MQs from the ascites of ovarian cancer patients and was positively correlated with C-X-C chemokine receptor 1/2 (CXCR1/2) expression in tumor cells." (PMID 39937005, 2025). "The coordinated levels of ROS, p-GSK-3β (Ser9), p-p70S6K (Thr389), and CXCL8 from ovarian cancer may be used as new biomarkers for ovarian cancer development and prognosis." (PMID 39660100, 2025). "CXCL8 also plays a role in aiding this process within ovarian cancer cells." (PMID 39595551, 2024). "In ovarian cancer (OC) cells, the tumor-promoting functions of IFNγ are mediated by IFNγ-induced expression of Bcl3, PD-L1 and IL-8/CXCL8, which have long been known to have critical cellular functions as a proto-oncogene, an immune checkpoint ligand and a chemoattractant, respectively." (PMID 39123403, 2024). "Moreover, we analyzed the plasma levels of CXCL1 and CXCL8 in ovarian cancer patients at various stages of the disease and observed a significant increase in their levels with disease progression." (PMID 37762405, 2023). "Finally, we found that the concentration of CXCL1 and CXCL8 in the plasma of ovarian cancer patients increased with stage progression." (PMID 37762405, 2023).
ovarian carcinoma (continued). "Our results demonstrated that inhibitors of CXCL8 significantly decreased the progression of ovarian cancer cells, indicating that the development of chemokine inhibitors may effectively suppress the progression of ovarian cancer." (PMID 37762405, 2023). "Next, we investigated whether CXCL8 secreted by catecholamines in ovarian cancer cells could induce cell invasion." (PMID 37762405, 2023). "In ovarian cancer, IL-8 (CXCL8) recruits neutrophils to the TME." (PMID 36831623, 2023). "We observed that bevacizumab could interact with CXCL8, which had been demonstrated to be a well-known anti-tumor drug for endometrial cancer and ovarian cancer." (PMID 36291687, 2022). "In addition, higher expression of CXCL8 has been noted in ovarian cancer cell lines with high metastasis compared with the parental cell lines." (PMID 36072669, 2022). "Nonetheless, it has been demonstrated that ectopic expression of CXCR2 in T-cells from normal donors or tumor-associated lymphocytes from ovarian cancer patients can increase their migration towards recombinant IL-8 and autologous ascites that contains CXCL1 and CXCL8 (IL-8)." (PMID 31091832, 2019). "Furthermore, CXCL8 is also upregulated in tumor-derived B cells isolated from ovarian cancer patients, in which B cells are present in TLS and also associate with improved prognosis." (PMID 30972056, 2019). "CXCL8 levels in ascites due to ovarian cancer, positively correspond to angiogenetic effectiveness." (PMID 30680411, 2019). "S1P also increases IL-8/CXCL8 expression in ovarian cancer cells such as HEY, OCC1 and SKOV3." (PMID 29467963, 2018). "Ovarian cancer (OC), the most common cause of cancer deaths among gynecological malignancies, is characterized by an increased expression of the pro-inflammatory and pro-angiogenic chemokine interleukin-8 (CXCL8, IL8)." (PMID 29050320, 2017). "We next determined whether CXCL1, CXCL2 and CXCL8 were required for proliferation and survival of ovarian cancer cells with GAB2 overexpression." (PMID 26657155, 2016). "Indeed, we showed that inhibition of IKKβ not only significantly reduced expression of CXCL1, CXCL2 and CXCL8, but also suppressed clonogenic growth of ovarian cancer cells as a single agent." (PMID 26657155, 2016). "Taken together, in consonance with previous observations, our results suggest that CXCL1, CXCL2 and CXCL8 could act as autocrine growth factors that directly promote proliferation and survival of ovarian cancer cells that overexpressed GAB2." (PMID 26657155, 2016). "The advanced stages of ovarian cancer are characterized by the increased expression of the pro-inflammatory and pro-angiogenic chemokine IL-8 (CXCL8), which induces tumor cell survival, proliferation, angiogenesis, and metastasis, and correlates with poor prognosis." (PMID 26267322, 2015). "Moreover, an ovarian cancer study demonstrated the ability of X1/2pal-i3 to attenuate CXCL1/CXCL8-induced endothelial cell proliferation and tube formation in vitro." (PMID 24276377, 2013). "Also, our previous studies have reported that TNF primarily induces CXCR2 ligands (CXCL1-3 and CXCL8) in ovarian cancer cells." (PMID 24376747, 2013). "Ovarian carcinoma ascitic fluid has also been found to contain high levels of CXCL8." (PMID 23300534, 2012). "Furthermore, we measured the expression of receptors for CXCL1 and CXCL8 in ovarian cancer cells and demonstrated that specific antibodies, receptor inhibitors, and CXCL8 antibodies SB225002 and SB265610, significantly inhibited ovarian cancer cell invasion induced by epinephrine." (PMID 37762405, 2023). "In addition, the overexpression of CXCL8 in ovarian cancer cells activates mitogen-activated protein kinase (MAPK) signaling and signal transducer activator of transcription 3 (STAT3), which in turn increases the expression of VEGF and decreases the level of thrombospondin-1 (TSP-1)." (PMID 37762405, 2023).